PFAS (phosphoribosylformylglycinamidine synthase)
Description:
Phosphoribosylformylglycinamidine synthase involved in the purines biosynthetic pathway. Catalyzes the ATP-dependent conversion of formylglycinamide ribonucleotide (FGAR) and glutamine to yield formylglycinamidine ribonucleotide (FGAM) and glutamate.
Synonyms: FGAMS; FGAR-AT; KIAA0361; PURL; FGARAT; GATD8
Tractability: PROTAC: ubiquitination databases record sites on it; its protein half-life has been measured.
Target class: Enzyme; Ligase
Gene: Protein-coding gene on chromosome 17 (8,247,618 to 8,270,491, forward strand). Ensembl gene ENSG00000178921.
Subcellular location: Cytoplasm
Subcellular location (Human Protein Atlas): Vesicles
Pathways (Reactome):
Metabolism: Purine ribonucleoside monophosphate biosynthesis
Gene Ontology:
Molecular function: phosphoribosylformylglycinamidine synthase activity
Biological process: 'de novo' AMP biosynthetic process; 'de novo' IMP biosynthetic process; 'de novo' XMP biosynthetic process; GMP biosynthetic process; purine nucleotide biosynthetic process; purine ribonucleoside monophosphate biosynthetic process; glutamine metabolic process; response to xenobiotic stimulus
Cellular component: extracellular exosome; cytosol; cytoplasm
Genetic constraint (gnomAD): Loss-of-function variants: 91 observed, 139.45 expected, observed/expected ratio (o/e) 0.65, 90% interval 0.55 to 0.78. The upper end of that interval is the gene's LOEUF score, 0.78, which puts it in group 3 of 6, group 1 being the genes least tolerant of losing a copy. Missense variants: 1,601 observed, 1,774.9 expected, observed/expected ratio (o/e) 0.9, 90% interval 0.87 to 0.94. Synonymous variants: 665 observed, 713.47 expected, observed/expected ratio (o/e) 0.93, 90% interval 0.87 to 0.99.
Homologues: Orthologues: chimpanzee PFAS (99% identical), macaque PFAS (97% identical), rabbit PFAS (90% identical), dog PFAS (89% identical), rat Pfas (89% identical), mouse Pfas (88% identical), guinea pig PFAS (88% identical), tropical clawed frog pfas (65% identical), zebrafish pfas (62% identical), Drosophila melanogaster Pfas (50% identical), Caenorhabditis elegans pfas-1 (47% identical).
Diseases named in the same sentence as PFAS in open-access papers:
PFAS is named in the same sentence as 20 diseases in open-access papers, as found by Europe PMC text mining. Sharing a sentence is not in itself a finding about the gene and the disease. The quoted sentences say what the papers report.
retinoblastoma (5 papers, 2023 to 2025). A malignant tumor that originates in the nuclear layer of the retina. "Hypermethylation of m5C in PFAS mRNA turns them into oncogenes that are highly expressed in retinoblastoma." (PMID 41150792, 2025). "ALYREF contributes to the NSUN2/PFAS oncogenic cascade by enhancing the stability of PFAS mRNA during retinoblastoma progression." (PMID 39664561, 2024).
viral infection (3 papers, 2011 to 2023). "Many substrates, such as PFAS, hnRNP K, and ALIX, generated similar cleavage products in vitro and during virus infection, and these cleavage products were stable in virus-infected cells." (PMID 29437971, 2018). "Notably, PFAS is an essential enzyme in the de novo synthesis of purines, playing an important role in RIG‐I activation during viral infection, autophagic regulation and carcinogenesis." (PMID 37228185, 2023).
Alzheimer disease (1 paper, 2021). A progressive, neurodegenerative disease characterized by loss of function and death of nerve cells in several areas of the brain leading to loss of cognitive function such as memory and language. "For instance, there are multiple, distinct lines of evidence linking PFAS (phosphoribosylformylglycinamidine synthase) to Alzheimer’s Disease." (PMID 33411734, 2021).
diabetes (1 paper, 2021). "These included several genes not previously implicated in diabetes, GIGYF1, TNRC6B and PFAS, as well as GCK, HNF1A and PDX1, known MODY genes." (PMID 34732801, 2021).
endometrial cancer (1 paper, 2022). Primary or metastatic malignant neoplasm involving the endometrium (mucous membrane that lines the endometrial cavity). "CPTAC data show significantly higher PFAS protein expression in endometrial cancer compared to normal tissues." (PMID 35887124, 2022). "Thus, a significant amount of validation of PFAS as a drug target, and drug discovery and development research, would be needed to target PFAS in endometrial cancer." (PMID 35887124, 2022).
infection (5 papers, 2016 to 2025). The state of being infected such as from the introduction of a foreign agent such as serum, vaccine, antigenic substance or organism. "PFAS was also found to be upregulated in Culex quinquefasciatus after infection with West Nile virus." (PMID 35369489, 2022). "There was no detectable decrease in the full-length ALIX, ACLY, hnRNP K, RIPK1, GBF1, and PFAS proteins, suggesting that only a subset of these target proteins are cleaved during infection." (PMID 29437971, 2018). "Immunoblotting for wild-type FLAG-tagged proteins detected cleavage fragments of ALIX, PFAS, and hnRNP K similar to those observed in vitro, indicating that the cleaved N-terminal protein fragments are stable and persist during infection." (PMID 29437971, 2018). "In contrast to the wild type, FLAG-tagged mutant ACLY, PFAS, hnRNP K, ALIX, and p115 resistant to 3Cpro cleavage in vitro were also resistant to cleavage during infection." (PMID 29437971, 2018).
tumor (5 papers, 2021 to 2026). "To further demonstrate the function of signalling cascade of NSUN2‐PFAS in the tumorigenesis of RB, we have tested the tumour proliferative ability in the orthotopic xenograft model by reintroducing PFAS in NSUN2‐deficient cells." (PMID 37228185, 2023). "In this study, we initially demonstrated that NSUN2 is necessary for PFAS activation by enhancing its RNA stability in RB, which expands the current understanding of dynamic m5C function during tumour progression." (PMID 37228185, 2023). "Taken together, these results indicate that PFAS is tumour‐specifically upregulated in RB." (PMID 37228185, 2023). "Activation of the mitogen-activated protein kinase (MAPK)/extracellular signal-regulated kinase (ERK) pathway stimulates PFAS phosphorylation at Thr2 via ERK2, facilitating the production of purine intermediates essential for cell proliferation and tumor growth." (PMID 41158760, 2026).
cancer (4 papers, 2018 to 2023). A tumor composed of atypical neoplastic, often pleomorphic cells that invade other tissues. "In preclinical studies, acivicin, an analog of glutamine, was shown to inhibit PFAS and other enzymes involved in purine salvage, resulting in growth inhibition of various cancer cell lines." (PMID 35887124, 2022). "ERK2 can phosphorylate T619 phosphorylation of phosphoribosylformylglycinamidine synthase in rat sarcoma viral oncogene (RAS)‐driven cancer cells to affect the activity of critical purine enzyme." (PMID 35092699, 2022). "Widespread shallow deletions for PFAS were also found in LUSC and PRAD, and copy number gains for PRKAG2 were found across the entire pan-cancer cohort." (PMID 36831501, 2023).
PFAS also shares sentences with these, for which no sentence is quoted: bladder cancer (1 paper); esophageal squamous cell carcinoma (1); folate deficiency (1); gastric cancer (1); leukaemia (1); lymph node metastasis (1); maturity-onset diabetes of the young (1); neuroblastoma (1); osteosarcoma (1); pancreatic cancer (1); pneumonia (1); streptococcal infection (1).